AFDN (afadin, adherens junction formation factor)
Description:
Belongs to an adhesion system, probably together with the E-cadherin-catenin system, which plays a role in the organization of homotypic, interneuronal and heterotypic cell-cell adherens junctions (AJs) (By similarity). Nectin- and actin-filament-binding protein that connects nectin to the actin cytoskeleton. May play a key role in the organization of epithelial structures of the embryonic ectoderm (By similarity). Essential for the organization of adherens junctions.
Synonyms: AF6; MLLT4; AF-6; MLL-AF6; l-afadin
Tractability: Small molecule: a structure with a bound ligand is known. Antibody: its Gene Ontology location is reachable by antibodies, with high confidence; the Human Protein Atlas places it where antibodies can reach. PROTAC: ubiquitination databases record sites on it.
Gene: Protein-coding gene on chromosome 6 (167,826,859 to 167,972,023, forward strand). Ensembl gene ENSG00000130396.
Subcellular location: Cell junction, adherens junction
Subcellular location (Human Protein Atlas): Cell Junctions; Plasma membrane; Nucleoplasm
Pathways (Reactome):
Cell-Cell communication: Adherens junctions interactions
Gene Ontology:
Molecular function: actin filament binding; cadherin binding; protein binding; small GTPase binding
Biological process: bicellular tight junction assembly; establishment of endothelial intestinal barrier; negative regulation of cell migration; pore complex assembly; positive regulation of cell-cell adhesion; positive regulation of cell-cell adhesion mediated by cadherin; positive regulation of gene expression; adherens junction maintenance; cell adhesion; cell-cell adhesion mediated by cadherin; cell-cell signaling; establishment of protein localization to plasma membrane; signal transduction; cell differentiation; cell junction organization
Cellular component: cell junction; cell-cell contact zone; cell-cell junction; nucleoplasm; plasma membrane; pore complex; tight junction; adherens junction; cytosol; cytoplasm
Genetic constraint (gnomAD): Loss-of-function variants: 59 observed, 183.92 expected, observed/expected ratio (o/e) 0.32, 90% interval 0.26 to 0.4. The upper end of that interval is the gene's LOEUF score, 0.4, which puts it in group 1 of 6, group 1 being the genes least tolerant of losing a copy. Missense variants: 1,961 observed, 2,205.1 expected, observed/expected ratio (o/e) 0.89, 90% interval 0.86 to 0.92. Synonymous variants: 812 observed, 811.38 expected, observed/expected ratio (o/e) 1, 90% interval 0.94 to 1.06.
Homologues: Orthologues: chimpanzee AFDN (99% identical), macaque AFDN (98% identical), dog AFDN (94% identical), mouse Afdn (93% identical), guinea pig AFDN (93% identical), rat Afdn (92% identical), pig AFDN (87% identical), tropical clawed frog afdn (78% identical), zebrafish afdna (75% identical), rabbit AFDN (61% identical), Drosophila melanogaster cno (37% identical), Caenorhabditis elegans afd-1 (27% identical).
Diseases named in the same sentence as AFDN in open-access papers:
AFDN is named in the same sentence as 30 diseases in open-access papers, as found by Europe PMC text mining. Sharing a sentence is not in itself a finding about the gene and the disease. The quoted sentences say what the papers report.
leukemia (34 papers, 2011 to 2024). A malignant (clonal) hematologic disorder, involving hematopoietic stem cells and characterized by the presence of primitive or atypical myeloid or lymphoid cells in the bone marrow and the blood. "This suggests the AF4, ENL, AF10 and AFDN fusion oncoproteins require the appropriate lineage context to thrive, and efficiently initiate and reinforce the corresponding lineage subtype of leukemia." (PMID 39472576, 2024). "The genes in the leukemia cell line term were AFDN (alias MLLT4, chromosome 1, WHWT), KLF3 (chromosome 3, LR), RPS6, (chromosome 5, LR), and FCER2, MCOLN1, and PRAM1 on chromosome 20 (GSD)." (PMID 36482174, 2022).
breast carcinoma (11 papers, 2011 to 2022). "We next interrogated publicly available RNA sequencing data sets from The Cancer Genome Atlas (TCGA) for associations between CLDN2 and AFDN mRNA expression and breast cancer subtype and outcome." (PMID 30692208, 2019).
CNS leukemia (3 papers, 2011 to 2020). "CASK and AFDN have also been implicated in CNS diseases such intellectual disabilities and CNS leukemia, respectively." (PMID 32984858, 2020).
low grade glioma (1 paper, 2019). A grade I or grade II glioma arising from the central nervous system. "CD155 can form the same complex with CD96, CD226, AFDN, ITGAV, ITGB3, and AFDN in low-grade glioma (LGG) and GBM samples derived from the Biological Pathway Ex-change (BioPAX)." (PMID 31377744, 2019).
cancer (20 papers, 2013 to 2024). A tumor composed of atypical neoplastic, often pleomorphic cells that invade other tissues. "Genes containing AS events associated with overall survival are known components of cancer-related pathways, including regulation of transcription (E2F4, ZNF730, GPBP1, POLR2J, SP2, and CIART), cell cycle (E2F4 and GTSE1), or cell-cell adhesion (CEACAM1, MMP14, EPS8L2, AP3D1, AFDN, and PAK4)." (PMID 35044822, 2022). "Despite this, AFDN plays a key role in regulating cell adhesion in metazoans and signalling from RAS subfamily GTPases to AFDN could have important implications for metastasis in RAS-driven cancers." (PMID 35931706, 2022). "For example, genes such as VEGFA and EZR were significantly expressed in EC-1-Cancer cells, but genes such as PDE4D and AFDN were not expressed." (PMID 37124501, 2023). "While RAS binding to AFDN may not directly stimulate proliferation, the metastatic nature of RAS mutant cancers makes study of this GTPase-effector complex a high priority." (PMID 35931706, 2022).
tumor (11 papers, 2011 to 2023). "The study of CTNNA3 and AFDN in skeletal muscle has not been reported, but there are many studies on them in tumor cells, mostly related to tumor cell proliferation and migration." (PMID 35484498, 2022).
AFDN also shares sentences with these, for which no sentence is quoted: acute myeloid leukemia (13 papers); colorectal cancer (3); acute leukemia (2); lung carcinoma (2); Parkinson disease (2); acute lymphoblastic leukemia (1); Alzheimer disease (1); cardiovascular disease (1); cerebral cavernous malformation (1); cervical carcinoma (1); colon cancer (1); diabetes (1); endometrial cancer (1); keratoconus (1); liver diseases (1); liver fibrosis (1); non-alcoholic steatohepatitis (1); pancreatic cancer (1); renal clear-cell carcinoma (1); sarcoma (1); spina bifida (1); systemic inflammatory response syndrome (1); testicular cancer (1); α-synucleinopathies (1).